CCNA2 (cyclin A2)
Diseases named in the same sentence as CCNA2 in open-access papers (continued):
Sharing a sentence is not in itself a finding about the gene and the disease.
cancer (continued). "Previous studies have confirmed that CCNA2 was elevated in various cancers." (PMID 40345591, 2025). "Recent studies have identified that CCNA2 may enhance cancer invasion, recurrence, metastasis, and chemoresistance." (PMID 40487391, 2025). "HBV integration frequently targets cancer-associated genes like human telomerase gene (TERT), the lysin methyltransferase 2B (KMT2B), cyclin E1 (CCNE1), and cyclin A2 (CCNA2), fragile genomic sites, and repetitive sequences, enhancing HCC risk (26, 27, 33, –, 37)." (PMID 40699151, 2025). "CCNA2, TTK, TOP2A, AURKA, AURKB and BUB1B are also closely associated with cancer." (PMID 39537209, 2024). "In addition, overexpression of CCNA2 enhances cancer cell multiplication, as well as metastasis and invasion." (PMID 37335738, 2023). "It had been proved that CCNA2 might be implicated in the epithelial-mesenchymal transitions (EMT) and cancer metastasis." (PMID 37064084, 2023). "Exclusive cyclin A2 or cyclin complex-targeting molecules are important in inhibiting the cell cycle and thus cancer cell proliferation, therefore these inhibitors might be useful for the treatment of AR-V7-expressing CRPC." (PMID 36937454, 2023). "Disease-free survival (DFS) data indicates high expression of CCNA2 is related to poor prognosis in cancers of ACC (p = 0.0057), BLCA (p = 0.049), KIRP (p < 0.001), LGG (p < 0.001), LIHC (p = 0.0039), PAAD (p = 0.038), PRAD (p = 0.0015), SARC (p = 0.0014), THCA (p = 0.0025), UVM (p = 0.0064)." (PMID 35480884, 2022). "CCNA2 was positively correlated with expressions of CD274, CTLA4, HAVCR2, LAG3, PDCD1, and TIGIT in most cancer types, which indicated the CCNA2 expression may act as a marker after immunotherapy." (PMID 35480884, 2022). "CCNA2 was differentially expressed in most cancer types vs. normal tissues." (PMID 35401923, 2022). "Interestingly, in small sets of patients with HCC, AAV showed insertional oncogenic mutagenesis similar to HBV, with a common hot spot of viral insertion within TERT, CCNE1, and CCNA2 cancer driver genes, leading to their overexpression." (PMID 36316711, 2022). "To date, only several studies assessed the immune role of CCNA2 in cancers." (PMID 35401923, 2022). "However, it is unable to retrieve any available reports about a pan-cancer analysis of the CCNA2 expression across all cancer types." (PMID 35480884, 2022). "Furthermore, CCNA2 is positively associated with expressions of immune checkpoints (CD274, CTLA4, HAVCR2, LAG3, PDCD1, and TIGIT) in most cancer types." (PMID 35480884, 2022). "CCNA2 is a cyclin and commonly overexpressed in many cancers." (PMID 35933367, 2022). "The results indicated that CCNA2 mainly positively regulated Myc, G2M checkpoint, and E2F_target pathways while negatively regulated xenobiotic metabolism, myogenesis, fatty acid metabolism, and bile acid metabolism in most cancer types." (PMID 35401923, 2022). "Our study indicated that CCNA2 expression was significantly and positively correlated with the level of CD 4 T+ cell memory cells and M0 and M1 macrophage infiltration across various cancer types." (PMID 35401923, 2022). "Recently, several studies have identified that CCNA2 might enhance cancer aggressive behavior, relapse, metastasis, and chemoresistance." (PMID 35401923, 2022). "In addition, high CCNA2 expression was correlated with poor clinicopathological features in various cancers, especially for ccRCC." (PMID 35401923, 2022). "Due to its important role in cancer, CCNA2 has become a therapeutic target for many cancer types." (PMID 35480884, 2022). "It has been found that CCNA2 expression is increased in many types of cancer." (PMID 35933696, 2022). "We believe that our work could assist in predicting the prognosis of patients with many cancer types and deepen our understanding of the potential regulation mechanism of CCNA2." (PMID 35480884, 2022).
cancer (continued). "We also found that CCNA2 could significantly regulate most immunomodulators in various cancer types, which indicated that CCNA2 could determine immunotherapy benefit of those cancer types." (PMID 35401923, 2022). "Finally, the 5 RNAs, including CCNA2, MKI67, KIF11, miR-30a-5p, and VPS9D1-AS1, were further identified as candidate crucial RNAs associated with cancer." (PMID 35186743, 2022). "In addition, CCNA2 was also significantly correlated with endothelial cell and macrophage cell in various cancers, especially in THYM." (PMID 35401923, 2022). "Some studies have implied that CCNA2 is overexpressed in many types of cancers." (PMID 34257537, 2021). "CCNA2 has been reported to affect the cell cycle of various cancers." (PMID 34631522, 2021). "In this study, we demonstrated that, compared to cells with basal CCNA2 expression, cancer cells highly expressing CCNA2 are more addicted to PLK1 activity and show increased mitotic index values, leading to G2/M arrest and mitotic catastrophe, followed by apoptosis, in response to PLK1 inhibitors." (PMID 32486290, 2020). "Recent experimental data indicates that CCNA2 is a potential target for cancer therapy." (PMID 32219041, 2020). "CCNA2 is an oncogene in cancers and promote proliferation by regulating cell cycle and we showed that miR-545 might inhibit proliferation by suppressing CCNA2 expression in OS cells." (PMID 32537647, 2020). "Previous researches showed that CCNA2 could regulate cell cycle in cancers via controlling the G1/S and G2/M transitions." (PMID 32411535, 2020). "Because CCNA2 is an oncogene in many cancers and promote proliferation by regulating cell cycle, we think miR-545 might inhibit proliferation by suppressing CCNA2 expression in OS cells." (PMID 32537647, 2020). "Either way, as a consequence of CCNA2 upregulation, cancer cells mayface an unavoidable dependence on PLK1 to prevent mitotic catastrophe by disrupted spindle assembly." (PMID 32486290, 2020). "CCNA2 is frequently related to cell proliferation and expressed at high levels in many cancers." (PMID 30766610, 2019). "CCNA2 overexpression has been reported in numerous types of cancers." (PMID 30042885, 2018). "Consultation of cancer genome repositories such as cBioPortal, the COSMIC database and TumorPortal reveals a variety of other missense mutations within CDK–cyclins in the context of cancer (e.g. R168C in CDK5, R86Q CDK9, R378G in cyclin A2)." (PMID 30185601, 2018). "Whether there are any specific roles for cyclin A2 in DNA replication and mitosis that could potentially be targeted for cancer treatment remain unclear." (PMID 29207607, 2017). "We might infer that cell cycle played a medium role in correlations of CCNA2 and cancers; thus cell cycle was discussed next." (PMID 26543493, 2015). "Importantly, we detected increased mRNA half-lives for cancer-related transcripts such as CCNA2, CCNB2 and CDKN1A that were previously shown to be stabilized by ELAVL1." (PMID 24417896, 2014). "Finally, though CCNA2-Drug interaction network, we demonstrated the interactions between CCNA2 and several available cancer drugs." (PMID 24622579, 2014). "It is noteworthy that upregulation of Ccna2 is generally considered a marker of aggressive cancers." (PMID 25505565, 2013). "Several studies have indicated that a high level of cyclin A2 expression may be a marker of poor prognosis in cancers." (PMID 19684852, 2009). "For cancer cells with low level of cyclin A2, which are less responsive to chemotherapeutic agents, induction of differentiation might be an alternative strategy." (PMID 19684852, 2009).
cancer (continued). "Cyclin A2, which is essential for initiation and progression of DNA replication as well as for cell cycle progression through G1/S and G2/M transitions, is over-expressed in a variety of human cancers compared with normal cells and tissues." (PMID 19684852, 2009). "Oncogenes such as MYC, AKT1, AKT2, cyclins CCNA2, CCNB1, CCNB2, CCNE1, CCNE2 and cyclin-dependent kinases CDK1 and CDK4, which were upregulated under androgen treatment, exhibited a significantly reduced expression following PVT1 knockdown, thereby modulating cancer-associated oncogenic pathways." (PMID 41792045, 2026). "Additionally, three cancer cell subpopulations with distinct chemosensitivity profiles were identified; Subpopulation 2, characterized by high expression of CCNA2, UBE2C, and CENPF, demonstrated significantly reduced sensitivity to methotrexate, doxorubicin, cisplatin, ifosfamide, and etoposide." (PMID 42099775, 2026). "In addition to the aspect of survival and apoptosis induction, we demonstrated that RES alone could disrupt the cell cycle control of ovarian SKOV-3 cancer cells by downregulating cyclin A2 expression, thereby inducing S-phase arrest." (PMID 37242538, 2023). "Furthermore, CCNA2 is thought to be a core gene in many cancer types." (PMID 35480884, 2022). "However, CCNA2 is also negatively correlated with the immune checkpoints in a few cancer types." (PMID 35480884, 2022). "Finally, CIBERSORT was employed to evaluate the immune cell infiltration degree in pancancer, which illustrated that CCNA2 could determine M1 macrophage in nearly all the cancer type, which further validated the results above." (PMID 35401923, 2022). "Hence, these candidate molecular drugs might also possess potential efficacy for CCNA2 highly expressed cancer types." (PMID 35401923, 2022). "Therefore, we conducted a pan-cancer analysis of CCNA2 using the TCGA project." (PMID 35480884, 2022). "Thus, elevated cyclin A2 in KRAS mutant cancers may reflect anadaptation mechanism from this cell cycle stress at the S phase." (PMID 32486290, 2020). "Notably, CCNA2 is commonly related to cell proliferation and highly expressed in many cancers." (PMID 32154226, 2020). "Moreover, we detected the expression levels of miR-29c-3p and CCNA2 mRNA in clinical samples of cancer tissues by qRT-PCR, and the results showed that miR-29c-3p in EC epithelial tissues was significantly lower than that in normal tissues, while CCNA2 was highly expressed." (PMID 32154226, 2020). "Increasing evidence indicates cyclin A2, cyclin D1 and cyclin E1 are positively correlated with the development of chemotherapy resistance, while the knockdown or depletion of these proteins inhibits cancer cell proliferation and promotes apoptosis, increasing sensitivity to chemotherapeutic drugs." (PMID 33292277, 2020). "Moreover, research reveals that CCNA2 may be a candidate target of immunotherapy for many cancer patients." (PMID 33195410, 2020). "In addition, these observations also suggest that cyclin A2 expression may confer cancer cells resistance to apoptosis." (PMID 26517515, 2015). "Besides, an interaction network was constructed to show how CCNA2 and available anti-cancer drugs could interaction with each other." (PMID 24622579, 2014). "Next, we sought to explore how CCNA2 and available cancer drugs could influence each other." (PMID 24622579, 2014). "Moreover, ChIP-chip assays yielded a total of 48 genes enriched in at least three of the seven primary samples including genes associated with cell cycle such as ARGHEF2, CCNA2, CDKN2D, GAK2, ORCL6, PCPNP, and TACC1 and genes associated with cancer such as AR, AXIN2, IKBKG, ETS1, PTPN11, and WNT2B." (PMID 23300998, 2013). "Many malignancies exhibit overactivation of the CDK2- CCNA2 and CDK1-CCNA2 complexes, making them a promising target for cancer therapy." (PMID 39929880, 2025).
cancer (continued). "CCNA2, SFN, HMGA2, SOX2, and RBP2 have been identified as significant biomarkers for cancer diagnosis and prognosis, particularly in liver cancer." (PMID 40251374, 2025). "Genes encoding proteins such as cyclin-dependent kinase 2 (CDK2), cyclin-dependent kinase 4 (CDK4), CDC28 protein kinase 1B (CKS1B), cyclin A2 (CCNA2), and cyclin D1 (CCND1) play key roles in promoting cell division and cancer progression." (PMID 41003013, 2025). "Our analysis revealed that genes such as ARID3A, CCNA2, and DDX39A were consistently and significantly overexpressed in cancer tissues." (PMID 40735323, 2025). "Generally speaking, the protein encoded by CCNA2 can activate CDK2, which may participate in the occurrence and progression of various tumors by affecting epithelial-mesenchymal transition (EMT), metastasis, and may enhance cancer invasion, recurrence, and chemotherapy resistance." (PMID 38464517, 2024). "By integrating microarray and RNA sequencing datasets, we found that CDK1, CCNA2, and CCNB1 were significantly upregulated in OS samples than non-cancer samples." (PMID 38164289, 2024). "Cyclin A2/CDK-2, promotes cancer progression by driving the cell-cycle transition from S phase to G2 phase." (PMID 38801618, 2024). "After GluOC treatment, cyclin A2, cyclin B1 and CDK1 increased, while Y-27632 suppressed cell cycle progression in cancer cells." (PMID 39054484, 2024). "The results showed that CCNA2, CDK1, KIF11, MKI67, and PLK1 were significantly and positively correlated with CEP55 in pan-cancer." (PMID 37887301, 2023). "miR-125 regulates the proliferation of cancer cells through the inhibition of the expression of cell cycle regulatory proteins, CDK6 and Cyclin A2." (PMID 37958720, 2023). "The results showed that the protein expressions of BUB1 (P < 0.001), BUB1B (P = 0.025), CCNA2 (P < 0.001), and CDCA8 (P = 0.002) were significantly up-regulated in the cancer tissues." (PMID 37853361, 2023). "SCL/TAL1 interrupting locus (STIL) promotes proliferation, invasion, and cancer progression by regulating the expression of CDK1, CCNB2, CDC20, CCNA2, BUB1, and AURKB." (PMID 36661515, 2023). "The correlation heatmap showed the top five genes (CCNA2, CKAP2L, KIF11, MKI67 and PLK1) that were positively and significantly related to RRM2 in almost all TCGA cancers." (PMID 35740608, 2022). "For example, FOXM1 promotes cyclin A2, B1, D1 and VEGF transcription to modulate the cell‐cycle progression and angiogenic ability of cancer cells." (PMID 35313071, 2022). "Interestingly, CCNA2 could activate those signals in most cancer types." (PMID 35401923, 2022). "Univariate Cox regression analysis identified four genes (CCNB1, CCNA2, IL1A, and MMP3) that significantly affected patient survival based on the 27 anticolon cancer targets of THCQF." (PMID 35479514, 2022). "Cyclin A2 (CCNA2) belongs to the highly conserved cyclin family and is significantly overexpressed in various cancer types." (PMID 35360870, 2022). "CCNA2 and CCNB1 are 2 members of the cyclin family, which regulate cell proliferation and apoptosis, and have been closely related to cancer progress and patients’ survival." (PMID 34596112, 2021). "Among all cyclin genes analyzed, CCNA2, CCNE2, CCNB2, CCNB1, CCNF, and CCNE1 were most elevated in the included cancers." (PMID 33996604, 2021). "In our analysis, 6 out of 18 genes (EIF4A3, RAN, PSMA3, CCNA2, POLR2D, CDC27) were scored as SL hits against RB1 in at least two human cancer cell lines screens." (PMID 33591981, 2021). "Cyclin A2 (CCNA2) belongs to a strongly conserved cyclin family, promoting cell cycle transition in cancers." (PMID 34603443, 2021). "In various types of cancers, numerous studies have now documented a link between EIF4A3, SMC3, ESPL1, CDC25B, CCNA2, or AURKA and their response to therapy." (PMID 32454908, 2020). "Meanwhile, CDK1, CCNA2, CCNB2, BUB1B and CDC20 were classified as cancer-related genes, and RRM2 was an FDA approved drug target." (PMID 33083112, 2020).
cancer (continued). "Accumulating studies have demonstrated that several cell cycle–related genes such as CCNB1, CCNA2, and CDK1, which were also identified in the current study, are involved in the initiation and development of cancer." (PMID 31428132, 2019). "For example, we observe that PLK1, CCNB1/2, CCNA2, AURKB and BUB1B are shared across 6–9 cancer types and physically interact with several deregulated neighbouring genes in our activated modules." (PMID 31396397, 2019). "NPTX1 inhibits the level of Cyclin A2 in HCC, implicating an anti-cancer role of NPTX1 in cancer progression." (PMID 31113871, 2019). "Second, tandem duplications were larger in CCNE1-activated HCC (median = 39 kb) than in CCNA2-activated HCC (22 kb), and smaller in BRCA1-altered breast (9 kb) and ovarian (10 kb) cancers." (PMID 30531861, 2018). "Disappearance of indirect connections between STIL and CDK1 can be interpreted as loosening the control over several important cyclins (CCNA2 and CCNE1) and the key cell cycle protein CDK1 in cancer." (PMID 29370181, 2018). "Instead, we observed that several indirect interactions disappear in the “cancer” network, namely three indirect regulations connecting STIL protein to CCNA2, CCNE1 and CDK1." (PMID 29370181, 2018). "First, the number of RS1 rearrangements was higher in CCNA2-activated HCC (median = 269) than in CCNE1-activated HCC and BRCA1-altered breast and ovarian cancers." (PMID 30531861, 2018). "Of the top 207 transcripts annotated as ‘cell cycle’ by GO analysis, we focused on nine well-known cell cycle regulators (CCNA2, CCND1, CDK6, CHK1, CHK2, MAPK1, MAP2K1,SKP2, and TFDP1) for further analyses, due to their known functions in cancers." (PMID 26958940, 2016). "Most of the miR-22-regulated targets involved in carcinoma development pathway were recently validated, including MYCBP, MCM7, CDC25C, and CCNA2, all of which are responsible for the cell proliferation." (PMID 27738335, 2016). "In this study, we demonstrate that miR-188 exerts anti-cancer potential via downregulating multiple G1/S related genes, including CCND1, CCND3, CCNE1, CCNA2, CDK2 and CDK4." (PMID 25304455, 2014). "Besides, previous studies have shown that cancer patients with high level of cyclin A2 had better chemotherapy response and survival than those with reduced cyclin A2 and low expression of cyclin A2, indicating that the patients with high expression of cyclin A2 are more suitable for chemotherapy." (PMID 19684852, 2009). "Besides, the expression level of CDK1, CCNA2, CHEK1, KIF11, PLK1 and TTK was significantly elevated with cancer progression in LUAD." (PMID 38783288, 2024). "Similarly, the cyclin genes CCNA2 and CCNE1 are higher in precancer and cancer than controls (p < 0.0001, p < 0.0001)." (PMID 39672307, 2024). "Expression of innate immune system markers (APOBEC3A/B), DNA repair genes (BRCA1, BRCA2, PALB2, RAD51), cell cycle genes (CCNA2 and CCNE1), a cell proliferation gene (MELTF), and a T-cell regulator (Treg) marker (FOXP3) was elevated in cancer compared to precancer and controls." (PMID 39672307, 2024). "In addition, there was no change in the expression status of senescent markers such as Cyclin A2 and p21 in SAHA-treated cancer cells after Tpr expression inhibition." (PMID 37543653, 2023). "Cancer cells treated with ellagic acid from HCAE were incapable of completing their cell-cycle and halted the cell-cycle at DNA synthesis S-Phase, as demonstrated by decreased cyclin A2 expression levels with increasing ellagic acid concentration." (PMID 37256897, 2023). "As mentioned with inhibition of cyclin A2, CDK inhibitors are widely used to treat cancer." (PMID 36937454, 2023). "CCNA2 has an important role in promoting G1-S cell cycle progression by facilitating CCND1 regeneration and participating in processes such as chromosome instability, cancer cell function, and cell maturation." (PMID 37853361, 2023).